PPP1R35 (protein phosphatase 1 regulatory subunit 35)
Description:
During centriole duplication, plays a role in the centriole elongation by promoting the recruitment of the microtubule-binding elongation machinery through its interaction with RTTN, leading to the centriole to centrosome conversion. In addition, may play a role in the primary cilia assembly (By similarity).
Synonyms: C7orf47; MGC22793
Tractability: PROTAC: ubiquitination databases record sites on it.
Gene: Protein-coding gene on chromosome 7 (100,435,282 to 100,436,497, reverse strand). Ensembl gene ENSG00000160813.
Subcellular location: Cytoplasm, cytoskeleton, microtubule organizing center, centrosome; Cytoplasm, cytoskeleton, microtubule organizing center, centrosome, centriole
Subcellular location (Human Protein Atlas): Nucleoplasm
Gene Ontology:
Molecular function: protein binding; phosphatase binding
Biological process: positive regulation of centriole elongation; notochord morphogenesis; positive regulation of cilium assembly
Cellular component: centriole; centrosome
Genetic constraint (gnomAD): Loss-of-function variants: 23 observed, 15.36 expected, observed/expected ratio (o/e) 1.5, 90% interval 1.07 to 1.91. The synonymous counts are far from expectation, so gnomAD's model fits this gene poorly and the ratio says little. Missense variants: 409 observed, 267.31 expected, observed/expected ratio (o/e) 1.53, 90% interval 1.41 to 1.66. Synonymous variants: 196 observed, 124.34 expected, observed/expected ratio (o/e) 1.58, 90% interval 1.4 to 1.77.
Homologues: Orthologues: chimpanzee PPP1R35 (99% identical), macaque PPP1R35 (91% identical), dog PPP1R35 (84% identical), pig PPP1R35 (82% identical), guinea pig PPP1R35 (76% identical), mouse Ppp1r35 (72% identical), rabbit PPP1R35 (71% identical).
Diseases named in the same sentence as PPP1R35 in open-access papers:
PPP1R35 is named in the same sentence as 6 diseases in open-access papers, as found by Europe PMC text mining. Sharing a sentence is not in itself a finding about the gene and the disease. The quoted sentences say what the papers report.
microcephaly (2 papers, 2018 to 2024). A congenital or acquired developmental disorder in which the circumference of the head is smaller than normal for the person's age and sex. "PPP1R35 is a candidate ciliopathy gene, associated with microcephaly, intellectual disability and global developmental delay." (PMID 39136782, 2024). "Our data show that that PPP1R35 impacts the process of centriole elongation through a close relationship with a known microcephaly protein, RTTN, therefore suggesting that PPP1R35 may be one such candidate microcephaly gene." (PMID 30168418, 2018).
breast carcinoma (1 paper, 2025). "While the mechanisms of PPP1R35 in cancer progression are unclear, its expression suggests a role in breast cancer metastasis." (PMID 40650042, 2025).
PPP1R35 also shares sentences with these, for which no sentence is quoted: cancer (1 paper); ciliopathy (1); developmental delay (1); Intellectual disability (1).